APOF (apolipoprotein F)
Description:
Minor apolipoprotein that associates with LDL. Inhibits cholesteryl ester transfer protein (CETP) activity and appears to be an important regulator of cholesterol transport. Also associates to a lesser degree with VLDL, Apo-AI and Apo-AII.
Synonyms: Apo-F; LTIP
Tractability: Antibody: UniProt places it where antibodies can reach, with high confidence; UniProt predicts a signal peptide or a membrane-spanning region; its Gene Ontology location is reachable by antibodies, with medium confidence.
Gene: Protein-coding gene on chromosome 12 (56,360,568 to 56,362,857, reverse strand). Ensembl gene ENSG00000175336.
Subcellular location: Secreted
Pathways (Reactome):
Transport of small molecules: LDL remodeling
Gene Ontology:
Molecular function: protein binding; cholesterol binding; lipid transporter activity; signaling receptor binding
Biological process: cholesterol metabolic process; lipid metabolic process; lipid transport
Cellular component: extracellular region
Genetic constraint (gnomAD): Loss-of-function variants: 3 observed, 2.7 expected, observed/expected ratio (o/e) 1.11, 90% interval 0.47 to 1.88. That is too few expected variants to judge how well the gene tolerates losing a copy. Missense variants: 370 observed, 410.76 expected, observed/expected ratio (o/e) 0.9, 90% interval 0.83 to 0.98. Synonymous variants: 149 observed, 163.1 expected, observed/expected ratio (o/e) 0.91, 90% interval 0.8 to 1.05.
Homologues: Orthologues: chimpanzee APOF (99% identical), macaque APOF (97% identical), guinea pig APOF (65% identical), rabbit APOF (61% identical), dog APOF (60% identical), mouse Apof (57% identical), rat Apof (57% identical), zebrafish apof (23% identical), tropical clawed frog apof (19% identical).
Diseases named in the same sentence as APOF in open-access papers:
APOF is named in the same sentence as 52 diseases in open-access papers, as found by Europe PMC text mining. Sharing a sentence is not in itself a finding about the gene and the disease. The quoted sentences say what the papers report.
diabetes (4 papers, 2008 to 2024). "We observed MR evidence for associations between genetically regulated levels of 7 proteins and HF risk factors including: SPON1, CCL15, and ITIH3 with hypertension; SVEP1 and SPON1 with atrial fibrillation; FSTL3 and NRP1 with diabetes; and APOF, CCL15, ITIH3, and NRP1 with CHD." (PMID 38225249, 2024). "After adjustment for classical diabetes risk factors, glucose parameters (FPG, HbA1C), and plasma TG, we ultimately identified 4 apolipoproteins amongst 16 that remain significantly associated with new-onset T2D in individuals with prediabetes: apoE, apoF, apoJ, and apoL1." (PMID 35130909, 2022). "Lower expression in patients with diabetes was evident for SCPEP1, S100A11, LEP, PEBP1, SHGB, and APOF." (PMID 37792298, 2023).
atherosclerosis (3 papers, 2016 to 2025). A disease characterized by the build-up of fatty material and calcium deposition in the arterial wall resulting in partial or complete occlusion of the arterial lumen. "Large differences in apoB, apoCI, apoCIII,apoF, apoH, and LPa between CKD5 and CVD patients were found, underlining the factthat atherosclerosis in patients with CKD is a different process than that inpatients with classical CVD." (PMID 27600335, 2016). "Identified apolipoproteins areanti-atherogenic (apoAI, apoAII, apoAIV, apoCI, apoCII, and apoCIII) or atherogenic(apoB100, apoF) factors; however, our results showed that this simple division didnot explain the higher incidence of atherosclerosis and cardiac events in CKDpatients." (PMID 27600335, 2016). "Although the exact role of STAT2 in atherosclerosis has not been reported, genetic manipulation of the apoF/Stat2 locus supports an important role for STAT2-dependent type I IFN signaling and gene expression in atherosclerosis." (PMID 31588227, 2019).
COVID-19 (3 papers, 2021 to 2024). A disease caused by infection with severe acute respiratory syndrome coronavirus 2. "Finally, six plasma proteins were found to mediate the causal effect between LTL and COVID-19 outcomes, such as BDNF, QPCT, FAS, MPO, SFTPB, and APOF." (PMID 38882679, 2024). "Furthermore, six proteins partially mediated the causality of LTL on COVID-19 outcomes, including BNDF, QPCT, FAS, MPO, SFTPB, and APOF." (PMID 38882679, 2024). "In addition to ApoA-I, most of the apolipoproteins classically associated with HDLs were less abundant in COVID-19 HDL particles, including ApoA-II, ApoC-I, II, III, IV, ApoA-IV, ApoC-I, ApoJ, Apo(a), ApoE, ApoM, ApoD, ApoB100 and ApoF." (PMID 33504824, 2021).
hepatocellular carcinoma (3 papers, 2019 to 2021). A malignant tumor that arises from hepatocytes. "APOF can act as a tumor suppressor for hepatocellular carcinoma, and the decreased expression of APOF is associated with a poor prognosis." (PMID 33758613, 2021). "The members of the C/EBP family are important players involved in the regulation of ApoF expression in hepatoma cell lines." (PMID 31687155, 2019). "We used quantitative reverse-transcription polymerase chain reaction (qRT-PCR) to detect ApoF mRNA expression in HCC tissues and hepatoma cell lines (SMMC-7721, HepG2, and Huh7)." (PMID 31687155, 2019).
hyperlipidemia (3 papers, 2022 to 2025). "Evidence for vertical pleiotropy was observed in 95 exposure-outcome pairs, including associations suggestive of endometriosis contributing to risk of hyperlipidemia, prescription of antacids, and reduced levels of Apolipoprotein F and Bifidobacteriaceae." (PMID 41377979, 2025). "In a population study of people with normolipidemia and hyperlipidemia, the ApoF levels were 83.5 ± 4.8 μg/mL and 70.0 ± 6.3 μg/mL, and the TG contents were 93 ± 3 mg/dL and 301 ± 18 mg/dL." (PMID 38540406, 2024). "Given the considerable impact of donor race on ApoF levels, the effect of hyperlipidemia on plasma ApoF levels was re-evaluated in a donor subset containing only Caucasian subjects." (PMID 35016907, 2022). "We also determined how these hyperlipidemias impacted the activation status of ApoF through its binding to LDL and identified chemical and physical properties of LDL that influence ApoF binding." (PMID 35016907, 2022). "The effect of hyperlipidemia on plasma ApoF levels is not well understood." (PMID 35016907, 2022). "How hyperlipidemia alters total plasma ApoF and its binding to LDL are poorly understood." (PMID 35016907, 2022). "Little is known about how ApoF levels are influenced by hyperlipidemia." (PMID 35016907, 2022). "Therefore, ApoF is considered a protective factor against hyperlipidemia." (PMID 38540406, 2024). "Although some differences in ApoF levels between males and females and their response to hyperlipidemia were noted, ApoF levels between lipid phenotype groups were not different." (PMID 35016907, 2022).
liver fibrosis (3 papers, 2012 to 2025). "The APASHA model—consisting of APOF, PCSK9, AFM, S100A6, HbA1c %, and AZGP1—showed an excellent discriminatory capacity with an AUROC of 0.8875 (CI 0.82–0.96) to discriminate MASH, but not liver fibrosis." (PMID 40250425, 2025).
cervical cancer (2 papers, 2022 to 2023). A primary or metastatic malignant neoplasm involving the cervix. "For example, the core proteins such as FN1 and APOF were involved in the process of cervical cancer." (PMID 36498728, 2022). "By validating the hub proteins using the ELISA, the authors introduced ORM1 (Orosomucoid 1) and APOF (Apolipoprotein F) as novel potential plasma markers in high grade squamous intraepithelial lesion (HSIL) and cervical cancer." (PMID 38328436, 2023). "We performed Chi-square test and Kaplan–Meier analysis in the cervical cancer patients, to explore the relationship between ORM1/APOF expression and the clinicopathological factors as well as the survival prognosis." (PMID 36498728, 2022). "By validating the hub proteins using the ELISA, we found that ORM1 and APOF could be the new potential plasma biomarkers in HSIL and cervical cancer, and further functional studies are worth exploring." (PMID 36498728, 2022).
Hypertension (2 papers, 2022 to 2024). The presence of chronic increased pressure in the systemic arterial system. "ApoF levels were not impacted by lipid-lowering hypertension or diabetic medications." (PMID 35016907, 2022).
liver cancer (2 papers, 2019 to 2023). An epithelial or non-epithelial malignant neoplasm that arises from the liver. "Our research supported prior research on liver cancer cell lines that APOF expression is down-regulated in LIHC and is associated with low recurrence-free survival." (PMID 37312170, 2023). "Low ApoF expression was associated with several clinicopathological features such as liver cirrhosis, Barcelona Clinic Liver Cancer stage and tumor-node-metastasis stage." (PMID 31687155, 2019). "Low ApoF expression was significantly associated with liver cirrhosis (P = 0.007), Barcelona Clinic Liver Cancer (BCLC) stage (P = 0.020) and tumor-node-metastasis (TNM) stage (P = 0.049)." (PMID 31687155, 2019).
non-alcoholic fatty liver disease (2 papers, 2017 to 2024). "IGNIS was tested using apolipoprotein F (APO-F), a potential biomarker for non-alcoholic fatty liver disease (NAFLD)." (PMID 28935895, 2017). "Furthermore, circulating proteins, like ApoF and IGFBP-2, have been associated with non-alcoholic fatty liver disease, a risk factor for type 2 diabetes." (PMID 37889320, 2024).
Alzheimer disease (1 paper, 2025). A progressive, neurodegenerative disease characterized by loss of function and death of nerve cells in several areas of the brain leading to loss of cognitive function such as memory and language. "Similarly, we found that genetic liability to Alzheimer’s disease had causal effects on levels of APOF (p = 2.4*10−07), and IL32 (p = 7*10−11)." (PMID 40281223, 2025).
amyloid (1 paper, 2025). "In addition to neurogenesis, cell adhesion/inflammation, and synaptic signaling, cholesterol metabolism, and especially lipoproteins (APOA1, APOC1, APOC3, APOF), were associated with depressive symptoms when amyloid pathology was present." (PMID 41451799, 2025).
autoimmune disease (1 paper, 2021). A disorder resulting from loss of function or tissue destruction of an organ or multiple organs, arising from humoral or cellular immune responses of the individual to their own tissue constituents. "The expression of APOF affects the IFN‐α‐induced gene levels associated with autoimmune diseases." (PMID 33934566, 2021).
breast carcinoma (1 paper, 2023). "For tumorigenesis, since high CE was found to be positively associated with breast cancer, this is consistent with our findings that elevated APOF expression in tumors compared to normal tissue causes high cholesterol." (PMID 37312170, 2023).
Dyslipidemia (1 paper, 2024). "Moreover, in order to investigate whether the ApoF gene leads to dyslipidemia, serum TG and HDL-C contents were measured." (PMID 38540406, 2024).
endothelial dysfunction (1 paper, 2020). In vascular diseases, endothelial dysfunction is a systemic pathological state of the endothelium (the inner lining of blood vessels) and can be broadly defined as an imbalance between vasodilating and vasoconstricting substances produced by (or acting on) the endothelium. "In patients with nonsevere endothelial dysfunction, a first cluster of proteins (apolipoprotein F and E, glutathione peroxidase 3 [GPx3], and fibrinogen β chain) was up-regulated and down-regulated after the low-fat diet and the Mediterranean diet, respectively." (PMID 32903262, 2020).
glioma (1 paper, 2023). A benign or malignant brain and spinal cord tumor that arises from glial cells (astrocytes, oligodendrocytes, ependymal cells). "In terms of OS, we found that high-expression APOF was significantly associated with poor prognosis in glioma (GBMLGG), and low-expression APOF was significantly associated with poor prognosis in LIHC and pancreatic adenocarcinoma (PAAD)." (PMID 37312170, 2023).
Hepatic steatosis (1 paper, 2024). Steatosis is a term used to denote lipid accumulation within hepatocytes. "Recent research indicates a reduction in apoF levels in individuals with hepatic steatosis, with decreased hepatic apoF expression correlating with an atherogenic lipid profile characterized by elevated levels of triglycerides, non-HDL cholesterol, and diminished levels of HDL-cholesterol." (PMID 39596967, 2024).
Hypercholesterolemia (1 paper, 2022). An increased concentration of cholesterol in the blood. "This shows that hypertriglyceridemia ameliorates the rise in ApoF caused by hypercholesterolemia, consistent with that previously demonstrated by an independent approach." (PMID 35016907, 2022). "Although the concentration of LDL is higher in HyperTC plasma, this redistribution of ApoF in hypercholesterolemia causes a more than 2-fold increase in the amount of ApoF per LDL particle." (PMID 35016907, 2022). "However, in donors with combined hypercholesterolemia and hypertriglyceridemia, the elevated triglyceride ameliorated the rise in ApoF caused by hypercholesterolemia alone." (PMID 35016907, 2022). "We speculate that the increased association of ApoF with LDL in hypercholesterolemia may retard ApoF clearance." (PMID 35016907, 2022). "ApoF was increased 31% in hypercholesterolemia but significantly decreased (20%) by hypertriglyceridemia." (PMID 35016907, 2022). "ApoF was quantified by ELISA in normolipidemic, HyperTC, and hypertriglyceridemic (HyperTG) individuals plus in those with combined hypercholesterolemia and hypertriglyceridemia." (PMID 35016907, 2022). "One possible explanation for the disparity between ApoF synthesis and ApoF plasma levels in hypercholesterolemia is altered turnover of plasma ApoF." (PMID 35016907, 2022). "We found that hypercholesterolemia and hypertriglyceridemia uniquely alter both total ApoF levels and the portion of that ApoF that is LDL bound." (PMID 35016907, 2022). "Notably, however, compared with individuals with hypercholesterolemia only, ApoF levels in both HyperTC + TG males and females were reduced by ∼25%." (PMID 35016907, 2022). "This shows that hypertriglyceridemia nullifies the ApoF-raising effect of hypercholesterolemia." (PMID 35016907, 2022). "Diet-induced hypercholesterolemia in rabbits and hamsters increases plasma ApoF 2-fold." (PMID 35016907, 2022). "Thus, plasma ApoF levels and the activation status of this ApoF are differentially altered by hypercholesterolemia and hypertriglyceridemia." (PMID 35016907, 2022). "We previously reported that the ApoF content of LDL is increased in severe hypercholesterolemia." (PMID 35016907, 2022). "In addition to the HyperTC group, three other samples in the total study group (n = 200) had very low ApoF levels, one subject normolipidemic and two subjects with combined hypercholesterolemia and hypertriglyceridemia." (PMID 35016907, 2022). "However, ApoF was decreased compared with subjects with hypercholesterolemia alone." (PMID 35016907, 2022). "Interestingly, the fraction of plasma ApoF that is active (i.e., bound to LDL) is high in hypercholesterolemia but very low in hypertriglyceridemia." (PMID 35016907, 2022). "In subjects with both hypertriglyceridemia and hypercholesterolemia, ApoF levels were not different from normolipidemic controls." (PMID 35016907, 2022). "The lack of an ApoF response to hypercholesterolemia in this study is unexpected since ApoF is increased 2-fold in HyperTC animals." (PMID 35016907, 2022). "In both male and female subjects with combined hypercholesterolemia and hypertriglyceridemia, ApoF levels were not different from normolipidemic controls." (PMID 35016907, 2022).
hypertriglyceridemia (1 paper, 2022). A laboratory test result indicating elevated triglyceride concentration in the blood. "We report here that ApoF protein levels are increased in HyperTC humans but decreased in hypertriglyceridemia." (PMID 35016907, 2022). "Plasma ApoF was increased 31% in hypercholesterolemic plasma but decreased 20% in hypertriglyceridemia." (PMID 35016907, 2022). "Like that seen with the larger donor group, the higher ApoF in HyperTC subjects was ameliorated by concomitant hypertriglyceridemia." (PMID 35016907, 2022). "Compared with normolipidemic LDL, hypercholesterolemic LDL contained ∼2-fold more ApoF per LDL particle, whereas ApoF bound to LDL in hypertriglyceridemia plasma was <20% of control." (PMID 35016907, 2022). "Hypertriglyceridemia also normalized ApoF levels in subject with elevated TC." (PMID 35016907, 2022).
lipid metabolism disorder (1 paper, 2024). "In the present study, transcriptome-wide MeRIP-seq and bioinformatic analyses were performed on ApoF knockout mice with a lipid metabolism disorder." (PMID 38540406, 2024).
liver cirrhosis (1 paper, 2019). "Furthermore, low ApoF expression was highly associated with several clinicopathological indicators such as liver cirrhosis, BCLC stage, and TNM stage." (PMID 31687155, 2019). "As many patients had liver cirrhosis, most samples exhibited heterogeneity with respect to positive staining for ApoF expression." (PMID 31687155, 2019).
Obesity (1 paper, 2025). Accumulation of substantial excess body fat. "BMI-predictive proteins included established obesity markers and obesity-related proteins, including adiponectin, CRP, IGFBP1, IGFBP2, PRG4, SHBG, apolipoproteins (APOA4, APOF) and inflammatory response proteins (A2M, APCS, LBP, HSPG2, HP, AOC3, ITGB1, VNN1)." (PMID 39972214, 2025).
psoriasis (1 paper, 2025). An autoimmune condition characterized by red, well-delineated plaques with silvery scales that are usually on the extensor surfaces and scalp. "APOF was expressed in psoriatic skin samples but not in normal skin samples, suggesting a potential role in the pathogenesis of psoriasis." (PMID 40564099, 2025).
schizophrenia (1 paper, 2022). A major psychotic disorder characterized by abnormalities in the perception or expression of reality. "Lipid-binding proteins ApoB, ApoD, ApoF, and ApoM were reduced in patients with schizophrenia, whereas ApoE was increased." (PMID 34741130, 2022).
steatosis (1 paper, 2023). Increased lipid within the cytoplasm of cells. "The lower expression of APOB could contribute to the steatosis in Pi*ZZ AATD patients, as it has been similarly described for APOA1 and APOF in NAFLD." (PMID 37569847, 2023).